EMSLR (E2F1 mRNA stabilizing lncRNA)
Synonyms: EMS; BCCE4
Gene: Long non-coding RNA gene on chromosome 7 (101,308,258 to 101,314,800, forward strand). Ensembl gene ENSG00000232445.
Diseases named in the same sentence as EMSLR in open-access papers:
EMSLR is named in the same sentence as 10 diseases in open-access papers, as found by Europe PMC text mining. Sharing a sentence is not in itself a finding about the gene and the disease. The quoted sentences say what the papers report.
lung carcinoma (2 papers, 2023 to 2024). "EMSLR regulated the cell proliferation and differentiation by repressing the promoter activity of LncPRESS1 in lung cancer cell." (PMID 38017579, 2023). "Interestingly, high expression of AC092718.4, AL365181.2, or EMSLR was an independent prognostic factor and related to worse OS, PFS, and RFS (recurrence‐free survival) in lung cancer patients." (PMID 39431755, 2024).
colon cancer (1 paper, 2021). "EMSLR is upregulated in tissue from colon cancer patients in several datasets, and its expression is associated with poor prognosis." (PMID 34556693, 2021).
endometrial carcinoma (1 paper, 2021). A malignant tumor arising from the epithelium that lines the cavity of the uterine body. "In one study EMSLR was differentially expressed between patients with early and advanced stage endometrial carcinoma, where increased expression of EMSLR was associated with disease progression." (PMID 34556693, 2021).
lung adenocarcinoma (1 paper, 2022). A carcinoma that arises from the lung and is characterized by the presence of malignant glandular epithelial cells. "In order to study the effect of EMSLR depletion, we carried out RNAi mediated depletion in A549 lung adenocarcinoma cells by transfecting siRNAs that target different regions of EMSLR and we observed that both the siRNAs significantly depleted the endogenous EMSLR." (PMID 35169159, 2022).
tumor (3 papers, 2022 to 2024). "In this study, EMSLR has been discovered from a screen to identify upregulated lncRNAs in human cancers and we wanted to evaluate if depleting EMSLR inhibits the tumor-associated phenotypes." (PMID 35169159, 2022). "EMSLR depletion blocks the cells in G1 phase and inhibits the clonogenic ability indicating that it is essential for the tumor-related phenotypes." (PMID 35169159, 2022).
cancer (2 papers, 2022 to 2023). A tumor composed of atypical neoplastic, often pleomorphic cells that invade other tissues. "Depletion of oncogenes such as C-MYC is known to induce apoptosis in cancer cells and thus we wanted to evaluate if EMSLR depletion also results in apoptotic death." (PMID 35169159, 2022). "Thus, we propose that MYC-EMSLR-LncPRESS1 pathway is functional in cancer cells based on the following results: First, LncPRESS1 was upregulated after depletion of EMSLR." (PMID 35169159, 2022).
EMSLR also shares sentences with these, for which no sentence is quoted: bladder cancer (3 papers); bladder (1); bladder tumors (1); non-small cell lung carcinoma (1).